CFTR (CF transmembrane conductance regulator)
Diseases named in the same sentence as CFTR in open-access papers (continued):
Sharing a sentence is not in itself a finding about the gene and the disease.
cystic fibrosis (continued). "Aberrant CFTR results in cystic fibrosis and subsequent impaired fluid and pH homeostasis, contributing to the pathology in the lungs, pancreas, livers, intestine, and testis." (PMID 36935741, 2023). "Usually accompanied by Burkholderia cenocepacia infection, cystic fibrosis is caused by mutations in the cftr gene encoding the cystic fibrosis transmembrane conductance regulator (CFTR), which usually results in a deletion of phenylalanine at position 508 (△F508)." (PMID 37216179, 2023). "Cystic fibrosis is an autosomal recessive genetic disorder resulting from defects in the cystic fibrosis transmembrane conductance regulator (CFTR) protein, which in turn results in a multi-systemic disorder." (PMID 37575762, 2023). "Cystic fibrosis is a monogenetic disease induced by genovariation in the cystic fibrosis transmembrane conductance regulator (CFTR)." (PMID 37240093, 2023). "Of note, it has been estimated that restoring 5% of wild-type CFTR mRNA in the cytosol is enough to ameliorate cystic fibrosis symptoms, although a higher threshold is necessary to avoid complications later in someone’s life." (PMID 36678793, 2023). "We detail their application as cystic fibrosis disease model in the cystic fibrosis transmembrane conductance regulator (CFTR)-dependent forskolin-induced swelling (FIS) assay." (PMID 37314920, 2023). "As HAE cultures are widely utilized for studies of airway function in cystic fibrosis, in which dysfunctional CFTR channels result in chronic airway disease, we assessed the expression of CFTR in HAE cultures." (PMID 37635251, 2023). "The European Cystic Fibrosis Society 2019 annual report (a year before the widespread introduction of CFTR modulators in clinical practice) stated that the median survival was 19 years, as only about 25% of all patients were older than 30.9 years." (PMID 36941680, 2023). "Over the last decade, drugs targeting specific CFTR molecular defects have dramatically expanded the treatment options for people with cystic fibrosis (pwCF)." (PMID 37024122, 2023). "Exemplar cases include a patient with cystic fibrosis harbouring a novel exonic LINE1 insertion in CFTR and a patient with generalised arterial calcification of infancy with complex interlinked duplications involving exons 2–6 of ENPP1." (PMID 37558402, 2023). "The licensing of certain CFTR gene variations for new CFTR modulator therapy in individuals with cystic fibrosis has been supported by clinical research and in vitro test findings." (PMID 37893045, 2023). "This technology was first reported in the context of NIPD for several autosomal recessive conditions, including cystic fibrosis (CFTR), β-thalassaemia (HBB), and congenital adrenal hyperplasia (CYP21A2)." (PMID 39698301, 2023). "Consistently, our results indicate that dysfunctional CFTR channels alter susceptibility to SARS-CoV-2 infection, resulting in reduced viral entry and replication in Cystic Fibrosis cells." (PMID 36627352, 2023). "Cystic fibrosis (CF, OMIM 219700) is a genetic disorder caused by mutations in the Cystic Fibrosis Transmembrane Conductance Regulator (CFTR) gene, which consequently alters ion homeostasis." (PMID 37312128, 2023). "Ionocytes, present at approximately 1–2% of airway epithelial cell frequency, express high levels of ion transporters, including CFTR, the chloride transporter dysfunctional in patients with cystic fibrosis." (PMID 37635251, 2023). "Pathogenic CFTR gene variants are a cause of cystic fibrosis (CF, OMIM#219700), and CFTR-related disorders (CFTR-RD)." (PMID 38254935, 2023). "Inhaled antibiotics continue to be prescribed for cystic fibrosis patients who receive cystic fibrosis transmembrane conductance regulator (CFTR) modulators to treat chronic respiratory infections." (PMID 36631132, 2023).
cystic fibrosis (continued). "Data on the response of A234D variant (both untreated and treated with CFTR modulators) expressed in FRT (Fisher rat thyroid) and CFBE (cystic fibrosis bronchial epithelial) cells are also shown." (PMID 38026150, 2023). "Lastly, as HAE culture systems are employed extensively in cystic fibrosis research, we evaluate the expression and function of CFTR channels in BCi-NS1.1-derived HAE cultures." (PMID 37635251, 2023). "One notable example is cystic fibrosis (CFTR gene), a relatively frequent potentially lethal autosomal recessive disease." (PMID 37761826, 2023). "The advent of CFTR modulators represents a turning point in the history of cystic fibrosis management, changing profoundly the disease’s clinical course by improving mucosal hydration." (PMID 37780857, 2023). "To date, approximately 90% of people with cystic fibrosis (pwCF) are eligible for highly-effective triple-CFTR-modulatory therapy with elexacaftor/tezacaftor/ivacaftor (ETI) as demonstrated in clinical trials or in vitro testing." (PMID 37050906, 2023). "miR-193b also seems to be involved in the pro-tumoral effect of the cystic fibrosis transmembrane conductance regulator (CFTR)." (PMID 36674481, 2023). "The small molecule SRI-37240 and its potent derivative SRI-41315 can induce a prolonged pause at the stop codon and restore CFTR expression and function by suppressing PTC-associated cystic fibrosis in primary human bronchial epithelial cells." (PMID 36979640, 2023). "The gene responsible for cystic fibrosis is a regulator called the cystic fibrosis transmembrane conductance regulator (CFTR) gene." (PMID 37893045, 2023). "While the drug class known as CFTR-modulators have significantly improved outcomes for people with cystic fibrosis, patients still acquire chronic Pseudomonas aeruginosa infections." (PMID 37956290, 2023). "Among LV vectors, HIV-based expression of CFTR in the mouse epithelium resulted in a partial recovery of electrophysiological functions in cystic fibrosis knockout mice for at least 110 days." (PMID 36992407, 2023). "Cystic fibrosis is caused by a mutation in the CF transmembrane conductance regulator (CFTR) gene." (PMID 37324924, 2023). "For cystic fibrosis, two general PIs restored deltaF508 CFTR expression in the plasma membrane, although these were immature forms and so of limited therapeutic value." (PMID 37206923, 2023). "Some infants undergoing newborn screening (NBS) tests have inconclusive sweat chloride test (SCT) results that lead to the designation of Cystic Fibrosis Screen Positive, Inconclusive Diagnosis/CFTR-related metabolic syndrome (CFSPID/CRMS)." (PMID 36969284, 2023). "A rare synonymous mutation (c.1584G>A) in the cystic fibrosis transmembrane conductance regulator (CFTR) gene in a cystic fibrosis patient, who is homozygous for this sSNP, has been recently linked as causal for pathology." (PMID 37495112, 2023). "Most of the 2,100 CFTR gene variants reported to date are still unknown in terms of their disease liability in Cystic Fibrosis and their molecular and cellular mechanism that leads to CFTR dysfunction." (PMID 37006619, 2023). "CFTR dysfunction leads to cystic fibrosis and remodeling of bronchi and small airways, thereby increasing airway resistance and the emergence of pulmonary emphysema." (PMID 36226596, 2023). "We uncover an unexpected requirement for these kinases in control of the CFTR pathway, a key player in cystic fibrosis, and show that CDK8/19 inhibition can modulate mucus production in organoids and in vivo." (PMID 36545778, 2023). "Cystic fibrosis is an autosomal recessive multiorgan disease that affects the function of exocrine glands, caused by mutations in the transmembrane conductance regulator (CFTR) gene." (PMID 37446121, 2023). "Macrophages in Cystic Fibrosis exhibit intrinsic, CFTR-dependent, dysregulated type I IFN signalling following activation." (PMID 37235648, 2023).
cystic fibrosis (continued). "More than 2000 variations are described within the CFTR (Cystic Fibrosis Transmembrane Regulator) gene and related to large clinical issues from cystic fibrosis to mono-organ diseases." (PMID 37445855, 2023). "In total, there were 11 unique P/LP variants in three genes related to three genetic diseases: COL7A1 AR Epidermolysis bullosa dystrophica, ABCA4 Stargardt disease type 1, and CFTR cystic fibrosis." (PMID 36635046, 2023). "Development of small molecules to improve CFTR protein function, termed CFTR modulators, has substantially benefitted people with cystic fibrosis." (PMID 36901843, 2023). "These iPSC lines derived from the somatic cells of cystic fibrosis patients provide useful resources for disease modelling and research on the pharmacological response to CFTR regulators." (PMID 37274156, 2023). "ASL (airway surface liquid) volume and composition are strictly regulated by chloride and bicarbonate secretion via CFTR [CF (cystic fibrosis) transmembrane conductance regulator] and other transporters." (PMID 37967223, 2023). "Dysfunction of CFTR leads to cystic fibrosis, which is also characterised by defective autophagy, lipid metabolism and immune response." (PMID 37108830, 2023). "Cystic fibrosis is a common lethal single-gene disorder in Caucasians that is caused by a mutation of the gene on chromosome 7 encoding a transmembrane conductance regulator protein, CFTR." (PMID 36980869, 2023). "The recent elucidation of atomistic structures of Cl− channel CFTR provides opportunities for understanding the molecular basis of cystic fibrosis." (PMID 36694009, 2023). "Another genetic disorder surprisingly involving the mitochondria is cystic fibrosis, characterized by severe pulmonary dysfunction caused by mutations in the gene coding for the cystic fibrosis transmembrane conductance regulator (CFTR) and responsible for abnormal mucus secretions." (PMID 37232752, 2023). "IMPORTANCE The management of cystic fibrosis has been transformed recently by the advent of CFTR modulators, including lumacaftor-ivacaftor." (PMID 36971560, 2023). "P. aeruginosa OMVs also carry Cif (CFTR Inhibitory Factor), a protein that interferes with the endocytic cycling of the cystic fibrosis transmembrane conductance regulator (CFTR) chloride ion channel in host epithelial cells." (PMID 37755174, 2023). "Cystic fibrosis is an inherited disorder characterized by the malfunction of the CF transmembrane conductance regulator (CFTR) protein, which plays an essential role in maintaining the balance of salt and water in airway epithelial cells." (PMID 38045035, 2023). "The level of MCC impairment in FOXI1-KO ferrets was also similar to CFTRG551D/G551D cystic fibrosis ferrets removed from treatment with a CFTR modulator (VX-770) that corrects the gating defect in the CFTRG551D channel." (PMID 37730992, 2023). "CF (OMIM:219700) is a genetic disease caused by mutations in the cystic fibrosis transmembrane conductance regulator (CFTR) gene and is considered the most common severe monogenic disease inherited in an autosomal recessive fashion among populations of Western European ancestry." (PMID 37175488, 2023). "Ionocytes comprise only 0.5–1% of airway epithelial cells and are responsible for the majority of cystic fibrosis transmembrane conductance regulator (CFTR)-activity in the lung epithelium." (PMID 37626876, 2023). "Because it directly reflects the function of the Cystic Fibrosis Transmembrane conductance Regulator (CFTR), the nasal potential difference test (nPD) can not only be used as a reliable diagnostic test for CF but also to assess efficacy of experimental treatments." (PMID 37835841, 2023). "Malfunction of the CFTR protein results in cystic fibrosis, one of the most common hereditary diseases." (PMID 38109179, 2023).
cystic fibrosis (continued). "Cystic fibrosis is a multi-system, lethal, autosomal recessive disorder caused by defects in the gene encoding for the CF transmembrane conductance regulator (CFTR), an ATP-gated channel for the efflux of chloride and bicarbonate anions mainly expressed in the apical membrane of epithelial cells." (PMID 37443798, 2023). "The advent of Trikafta (Kaftrio in Europe) (a triple-combination therapy based on two correctors—elexacaftor/tezacaftor—and the potentiator ivacaftor) has represented a revolution for the treatment of patients with cystic fibrosis carrying the most common misfolding mutation, F508del-CFTR." (PMID 35292885, 2022). "Cystic fibrosis, the most common genetically inherited disease in Caucasian populations, is a multi-systemic life-threatening autosomal recessive disorder caused by mutations in the cystic fibrosis transmembrane conductance regulator (CFTR) gene." (PMID 36293274, 2022). "A total of 83 unique siRNAs or siRNA combinations were tested on cystic fibrosis bronchial epithelial (CFBE) mCherry-Flag-F508del-CFTR and wt-CFTR reporter cell lines for their ability to modulate the amount of PM-located CFTR." (PMID 35500936, 2022). "CF symptoms are caused by an imbalance in ion and water homeostasis in the secretory epithelia of these organs due to loss of function of the apical chloride and bicarbonate channel CFTR (cystic fibrosis transmembrane conductance regulator, see Section 2.1." (PMID 35740997, 2022). "The use of modulator drugs that target the Cystic Fibrosis transmembrane conductance regulator (CFTR) is the final frontier in the treatment of Cystic Fibrosis, a genetic multiorgan disease." (PMID 35631432, 2022). "Such is the case with Cystic Fibrosis, a monogenic recessive disease caused by mutations in the CFTR gene, which encodes the CF Transmembrane Conductance Regulator (CFTR) protein." (PMID 35269829, 2022). "The cystic fibrosis transmembrane conductance regulator (CFTR) is a cAMP-regulated chloride channel expressed on the plasma membrane (PM) of epithelial cells, where its mutation gives rise to cystic fibrosis, a recessive genetic disorder." (PMID 35355508, 2022). "As is well known, the majority of cystic fibrosis cases result from a CFTR mutation." (PMID 36476557, 2022). "The pathogenic variant Phe508del of the CFTR-gene is the most frequent cause of cystic fibrosis." (PMID 35115637, 2022). "Other type I correctors, such as C18 (VRT-534; from the Cystic Fibrosis Foundation’s CFTR Compound Program), ABBV-2222 (formerly GLPG-2222; also known as galicaftor), FDL-169 and trimethylangelicin (derivatives) rescue CFTR through a similar MoA." (PMID 35740997, 2022). "Compound heterozygosity for a major cystic fibrosis-causing variant and the modulator allele, IVS8-5T, in CFTR explained the recurrent upper and lower respiratory way infections, bronchiectasis, cholelithiasis, and chronic constipation." (PMID 35627274, 2022). "The possibility to upregulate CFTR expression is of great relevance in the possible personalized treatment of Cystic Fibrosis, a genetic disease that is characterized by a deep alteration of CFTR." (PMID 36012615, 2022). "CF is caused by mutations in the cystic fibrosis transmembrane conductance regulator (CFTR), an ion channel that conducts chloride and thiocyanate ions across epithelial cell membranes, leading to defective mucociliary clearance and polymicrobial infection, resulting in eventual pulmonary failure." (PMID 35972133, 2022). "In this study, we provided the estimated prevalence of cystic fibrosis in Chinese population based on a Chinese-specific CF screening panel consisting of manually curated CFTR pathogenic or likely pathogenic variants in a large-scale exome sequencing Chinese cohort." (PMID 35313924, 2022). "The importance of proper CFTR function is appreciated in cystic fibrosis and chronic obstructive pulmonary disease (COPD)." (PMID 35967318, 2022).
cystic fibrosis (continued). "4,6,4′-trimethylangelicin (TMA) is a promising pharmacological option for the treatment of cystic fibrosis due to its triple-acting behavior toward the function of the CF transmembrane conductance regulator." (PMID 36145554, 2022). "Cystic fibrosis is a complex systemic disease arising from autosomal recessive inheritance of dysregulation of the CF transmembrane conductance regulator (CFTR) membrane protein." (PMID 35891262, 2022). "Biofilms of P. aeruginosa PAO1 (GFP+) were cultured on confluent monolayers of CFTR −/− cystic fibrosis bronchoepithelial cells (CFBEs) for 6 h before treatment with PAAG (250 μg ml−1)." (PMID 35077346, 2022). "In cystic fibrosis, CFTR (cystic fibrosis transmembrane conductance regulator) mutations result in defective chloride transport at the epithelial cell membrane and disturbed water and electrolyte balance leading to thick mucus and decreased mucus clearance." (PMID 35505316, 2022). "The treatment of human cerebrovascular cells, placental cells, and bronchial epithelial cystic fibrosis cells, corrected or uncorrected for CFTR, by chloroquine (50 nM × 24 h), significantly reduced the ARSB activity, protein, and mRNA." (PMID 36361933, 2022). "CFTR is expressed at very high levels during fetal lung development, and patients with cystic fibrosis present with abnormal lung development as early as 17–19 weeks gestation." (PMID 35237593, 2022). "Drugs that improve the structure and function of CFTR have good therapeutic prospects in cystic fibrosis." (PMID 35773269, 2022). "In cystic fibrosis, the deletion of phenylalanine 508 (F508del)in the CF transmembrane conductance regulator (CFTR) leads to misfoldingand premature degradation of the mutant protein." (PMID 35377645, 2022). "CF occurs due to mutations in the cystic fibrosis transmembrane conductance regulator (CFTR) gene." (PMID 35832587, 2022). "Functional validations in multiple disease models uncovered proteins with potential roles in CFTR function and cystic fibrosis." (PMID 35156780, 2022). "Studying CFTR function of rectal organoids from cystic fibrosis patients and the organoid’s response to the drug treatments ivacaftor and lumacaftor." (PMID 34147034, 2022). "Ivacaftor, approved by FDA for cystic fibrosis therapy, is a potentiator of cystic fibrosis transmembrane conductance regulator (CFTR)." (PMID 35814272, 2022). "Cystic fibrosis transmembrane conductance regulator (CFTR) gene mutation causes CF." (PMID 35273961, 2022). "We thank John Riordan (University of North Carolina) and Cystic Fibrosis Foundation for antibodies against CFTR from Antibody Distribution Program." (PMID 35571097, 2022). "Overall, our results advance the understanding of how the NMD pathway regulates CFTR mRNAs containing nonsense codons and provides the direction for the development of therapeutic NMD inhibitors for cystic fibrosis caused by nonsense mutations." (PMID 35487895, 2022). "The last ten years have been characterized by an enormous step forward in the therapy and management of patients with Cystic Fibrosis, thanks to the development and combination of Cystic Fibrosis Transmembrane Receptor (CFTR) correctors and potentiators." (PMID 36498475, 2022). "CF is caused by pathogenic variants/mutations in the cystic fibrosis transmembrane conductance regulator (CFTR) gene and is characterised by a multiorgan pathology affecting the upper and lower airways, gastrointestinal and reproductive tracts and endocrine system." (PMID 36428953, 2022). "On the other hand, CFTR is permeable to not only chloride ions, but also organic anions such as reduced glutathione, and consequently CFTR dysfunction potently contributes to the OS burden at the airway surface in cystic fibrosis." (PMID 35143116, 2022). "Lumacaftor (VX-809), a CFTR corrector, is usually used in combination with ivacaftor for the treatment of cystic fibrosis." (PMID 35773269, 2022).